TNF (tumor necrosis factor)
Diseases named in the same sentence as TNF in open-access papers (continued):
Sharing a sentence is not in itself a finding about the gene and the disease.
atherosclerosis (continued). "In an in-vitro model of atherosclerosis, miR-130a overexpression enhanced inflammatory factors like tumor necrosis factor (TNF)-α and interleukin (IL)-1, IL-6, and IL-8 and its downregulation reduced the inflammation by attenuating TNF-α, IL-1, IL-6, and IL-8." (PMID 36430208, 2022). "Treatment of senescence-related chronic disease, as shown by recent studies with DPP4 inhibitors that ameliorated atherosclerosis in type 2 DM patients, prevented vascular aging and protected chondrocytes from TNF-α-induced senescence." (PMID 35251476, 2022). "A previous study showed that PN saponins from PN can suppress atherosclerosis, reduce NF-κB signaling activation and inhibit proinflammatory factors, including IL-6, IL-1β, TNF-α, and Calpain1 protein expression." (PMID 36501304, 2022). "TNF-α-induced monocyte-to-endothelial-cell adhesion assays have a long history and are frequently used, especially in the context of atherosclerosis research." (PMID 35579886, 2022). "The top five significant KEGG pathways of DEGs were enriched in Staphylococcus aureus infection, tumor necrosis factor (TNF) signaling pathway, Tuberculosis, Osteoclast differentiation, and Fluid shear stress and atherosclerosis." (PMID 35693550, 2022). "As previously discussed, VAT tends to stimulate the release of cytokines (such as IL-6 and TNF-a) and hormones that can lead to systemic inflammation, thereby increasing coagulation and adhesion molecules, contributing to atherosclerosis formation." (PMID 35492380, 2022). "Mouse treated with a combination of anti-CD47 and anti-TNF-α antibodies showed a better reduction in atherosclerosis than anti-CD47 alone." (PMID 36359349, 2022). "Rising plasma levels of TNF-α is associated with IL-6 and CRP in elderly people as well; TNF-α is correlated to atherosclerosis and Alzheimer’s in people over 100 years old78." (PMID 36496428, 2022). "Ascorbate and aldarate metabolism, drug metabolism, tyrosine metabolism, pyruvate metabolism, the TNF signaling pathway, the relaxin signaling pathway, the IL-17 signaling pathway, and fluid shear stress and atherosclerosis need further study." (PMID 36419834, 2022). "The knockdown of METTL14 led to the inhibition of the TNF-α-induced cell senescence, endothelial inflammation, and atherosclerosis development." (PMID 36052084, 2022). "Data obtained in table showed that, there was a significant elevation in the levels of CRP, IL-6 and TNF-α in obese with atherosclerosis patients and obese subjects compared with control group (p < 0.001)." (PMID 36407366, 2022). "The main functional pathways involved in these critical targets include fluid shear stress and atherosclerosis, lipid and atherosclerosis, IL-17 signaling pathway, age-range signaling pathway in diabetic composites, and TNF signaling pathway via KEGG analysis." (PMID 36619785, 2022). "The enriched KEGG pathways included TNF signaling pathway, Influenza A lipid and atherosclerosis pathway, linoleic acid metabolism, nicotinate and nicotinamide metabolism, glycine, serine, and threonine metabolism, and so on." (PMID 37008043, 2022). "In atherosclerosis, it exerts its protective effects via inhibition of inflammation (suppression of IL-1, IL-6, and TNF-α), oxidative stress, endothelial monocyte adhesion, and lesional foam cell apoptosis." (PMID 36555579, 2022). "For our analysis, we chose three cytokines that lead in the processes of atherosclerosis: interleukin 6 (IL-6), interleukin 18 (IL-18) and tumor necrosis factor α (TNF-α)." (PMID 35630041, 2022). "Some studies highlight the potential of anti-TNF-α agents (biologics) to reverse pre-existing subclinical atherosclerosis by reducing chronic inflammation." (PMID 35207718, 2022). "The increased inflammation cytokines, including IL-6, IL-1β, and TNF-α, are also the main characteristics of atherosclerosis." (PMID 36145277, 2022).
atherosclerosis (continued). "Increased fatty liver-induced proinflammatory cytokines such as IL-1β, IL-18, and TNF-α can affect the development of atherosclerosis." (PMID 36364718, 2022). "Tumor necrosis factor alpha (TNF-α), which is upregulated during atherosclerosis, promotes FSTL3 transcription by binding to four TNF-α sensitive repeats in its promoter region." (PMID 36325361, 2022). "miR-652-3p is highly expressed in atherosclerosis, miR-652-3p inhibitor decreased IL-1β, IL-6, and TNF-α expression after ox-LDL treatment." (PMID 36248191, 2022). "KEGG pathway enrichment analysis shows 241 signaling pathways, focusing on cancer, fluid shear stress and atherosclerosis, and TNF and PI3K/AKT signaling pathways." (PMID 35656461, 2022). "Released cytokines, including tumor necrosis factor-α (TNF-α), disrupt endothelial function and consequence in arterial stiffness and atherosclerosis." (PMID 36687438, 2022). "Upon TNF activation, ROS contribute to TNF-induced NF-kB activation, decreased NO bioavailability and progression of atherosclerosis." (PMID 35216481, 2022). "Puerarin was associated with cancer pathways, lipid and atherosclerosis, hepatitis B, cGMP signaling pathway, HIF-1 signaling pathway, TNF signaling pathway, cAMP signaling pathway, MAPK signaling pathway, and others according to KEGG enrichment analysis." (PMID 36299877, 2022). "Caffeic acid inhibited TNF-α-induced NF-κB-DNA complex formation and CAMs expression, suggesting its potential role in atherosclerosis diseases." (PMID 35215227, 2022). "Cytokines produced by B cells can enhance immunomodulation during chronic inflammation; for example, TNF-α, IL-2, and IL-10 produced by B2 cells promoted atherosclerosis." (PMID 34522782, 2021). "Findings concerning the effect of TNFα inhibitors on the progression of subclinical atherosclerosis in patients with RA are inconsistent." (PMID 35054229, 2021). "APN administration has been shown to prevent atherosclerosis by reducing the production of TNF-α in macrophages and reactive oxygen species (ROS) in endothelial cells; it also increases endothelial cell migration and angiogenesis." (PMID 34456867, 2021). "We have previously shown that Leukotriene D4 (LTD4) promotes endothelial dysfunction, increasing endothelial permeability and enhancing TNFα-mediated attachment of monocytes to endothelium, which hints at its possible role in atherosclerosis." (PMID 34867460, 2021). "Regular endurance exercise has been shown to reduce biomarkers associated with chronic, vascular inflammation and the development of atherosclerosis such as tumor necrosis factor alpha (TNF-α), interleukin 6 (IL-6) and C-reactive protein (CRP)." (PMID 34571843, 2021). "Common DEGs were linked to the cytokine-related pathways “Osteoclast differentiation”, “TNF signaling pathway”, and “Fluid shear stress and atherosclerosis”." (PMID 34428250, 2021). "IL-6, which is induced by pro-inflammatory cytokines such as IL-1 and TNF cytokines, acts as a central hub for atherosclerosis inflammatory signaling." (PMID 34071276, 2021). "Formation of foam cell and recruitment of circulating immune cells also contribute to the formation of the plaque’s necrotic core in the later stages of atherosclerosis when TNF-α critically contributes to vascular remodeling." (PMID 33770265, 2021). "Malnutrition, inflammation and atherosclerosis interact with inflammatory cytokines and tumor necrosis factor-α, eventually leading to endothelial dysfunction." (PMID 34945724, 2021). "These include the presence of pro-atherogenic LDL cholesterol in the subendothelial region that triggers an aortic inflammatory reaction by activating the TNF-α/NF-κβ pathway, hence accelerates the progression of atherosclerosis." (PMID 33921777, 2021). "Elevated ox-LDL levels are reported to be strongly positively linked to both atherosclerosis and inflammatory markers, including CRP, TNF-α and IL-6." (PMID 33670720, 2021).
atherosclerosis (continued). "In this study, resveratrol in concentrations as low as 1 μm suppressed TNF-α-induced monocyte adhesion to human EA.hy926 endothelial cells (ECs), a key event in the initiation and development of atherosclerosis." (PMID 34830366, 2021). "ox-LDL stimulates the secretion of TNF-α from macrophages and cytokines from ECs, indicates the starting point of atherosclerosis." (PMID 34803487, 2021). "Oxidative stress is a crucial factor of atherosclerosis pathophysiology and TNF-α induces ROS production in vascular tissue." (PMID 34961267, 2021). "Atherosclerosis is a chronic inflammatory disease and recent study indicated that atherosclerosis‐related inflammation is mainly mediated by pro‐inflammatory cytokines (IL‐1β, IL‐6 and TNF‐α) and inflammatory signaling pathways (Gisterå & Hansson, 2017)." (PMID 34592792, 2021). "TNF-α is produced by monocytes and macrophages, exists in atherosclerotic plaques, and participates in the formation of atherosclerosis." (PMID 34887932, 2021). "It has also been described that in later stages of atherosclerosis, cytokines such as TNF-alpha, INF-γ, IL-1, and IL-6 act differently, inducing smooth muscle cell apoptosis and matrix degradation, leading to plaque destabilization." (PMID 34205487, 2021). "The accumulation of oxidized lipids triggers atherosclerosis mediated by proinflammatory cytokines, such as interleukin-1β, tumor necrosis factor-α (TNF-α), and nuclear factor-κB (NF-κB)." (PMID 34835997, 2021). "Activation of the TNF-α pathway can induce oxidative stress and increase transcytosis of LDLs across endothelial cells and promote the development of atherosclerosis." (PMID 34746316, 2021). "Since the adhesion of inflammatory monocytes to endothelial cells is an important step in the development of atherosclerosis, we evaluated the possible role of Ataxin-10 on TNF-α-induced monocyte adhesion." (PMID 34858081, 2021). "S100A12 augmented the atherosclerosis-triggered osteogenesis and TNF-α increased the expression of RAGE." (PMID 34497344, 2021). "TNF-α significantly increases the vascular endothelial inflammatory response and atherosclerosis through nuclear factor kappa-B signaling." (PMID 34976297, 2021). "It has been reported that STS can reduce the expression of the inflammatory cytokines IL-6 and TNF-α in a mouse model of atherosclerosis." (PMID 34122723, 2021). "We have previously shown that sIgM deficiency aggravates atherosclerosis in mice and local PVAT mRNA levels of proinflammatory cytokines like INFγ and TNFα in sIgM−/− mice are significantly higher compared to littermate controls (unpublished data)." (PMID 33679793, 2021). "KEGG pathway enrichment analysis showed that the main pathways that regulate hyperlipidemia are the AGE-RAGE signaling pathway in diabetic complications, fluid shear stress, and atherosclerosis, the TNF signaling pathway, and the HIF-1 signaling pathway." (PMID 34746316, 2021). "In sum, for the first time, this LacCer-centric pathway connects pro-inflammatory cytokine TNF-α, which targets LacCer synthase, to the initial step of inflammation and atherosclerosis." (PMID 33673027, 2021). "The pro-inflammatory cytokines tumour necrosis factor alpha (TNF-α) and interleukin-6 (IL-6), which are involved in the pathogenesis of RA, are predictive of subsequent CV events, as both play important roles in atherosclerosis." (PMID 33259776, 2021). "In our previous studies, we demonstrated a significant increase of CTSC and macrophage M1 marker TNF-α in atherosclerosis cases compared with the control group." (PMID 34737793, 2021). "This reinforces miR-146 as a potential target in experimental models of SCAD, considering the key role of inflammation in the regulation of atherosclerosis, particularly the TNF-α pathway." (PMID 34199767, 2021).
atherosclerosis (continued). "Given the pathogenic role of proinflammatory cytokines in AIRD-related atherosclerosis, tight control of disease activity with biologic DMARDs, including TNF-α inhibitors, IL-6 inhibitors, and IL-17 inhibitors, may reduce the risk of ASCVD." (PMID 34066436, 2021). "Dapagliflozin also suppressed iNOS, TNF-α, IL-1β, and IL-6 mRNA expression by attenuating the NF-κB transcription factor in diet-induced atherosclerosis in rat aortic arteries." (PMID 34124273, 2021). "Several studies in animal models of atherosclerosis and inflammation suggest that bacterial lipopolysaccharides induce the secretion of pro-inflammatory TNF-α." (PMID 33673027, 2021). "Infection by Chlamydia pneumoniae, which is suggested to be one of the etiologic agents of atherosclerosis, stimulates the secretion of inflammatory cytokines (TNF-α, IFN-γ, IL-6, etc.) and leukocyte adhesion molecules." (PMID 34959604, 2021). "The KEGG enrichment of mainly enriched genes was cytokine-cytokine receptor interaction, malaria, fluid shear stress, and atherosclerosis, TNF signaling pathway, and Jak-STAT signaling pathway." (PMID 34749650, 2021). "Data from both experimental and epidemiological studies confirm a significant role of IL-6 and TNF-α, and especially IL-1β cytokines, in the development of atherosclerosis." (PMID 32378144, 2021). "IL-1β, IL-6, TNF-α, and CRP were previously evaluated for their potential to be therapeutic targets for anti-inflammatory treatment in atherosclerosis, thus reducing the residual risk of atherosclerotic cardiovascular disease." (PMID 34300308, 2021). "Soluble tumor necrosis factor receptors (sTNFR-1 and sTNFR-2) are shed in the context of TNF-alpha signaling and systemic inflammation, which play a role in atherosclerosis and plaque instability." (PMID 34988343, 2021). "LTB4 then goes on to induce overexpression of TNF-α and IL-6, thereby contributing to the development of an inflammatory environment in ailments such as atherosclerosis." (PMID 33878031, 2021). "Although quite different in origin, atherosclerosis and heart failure have in common the involvement of TNF in mediating the inflammatory response." (PMID 34439792, 2021). "Specifically, curcumin can inhibit cholesterol metabolism, while probucol can be used to treat atherosclerosis by inhibiting TNF-α-induced cholesterol metabolism." (PMID 34257809, 2021). "TNF-α is involved in the pathological process of atherosclerosis by increasing inflammatory cells in injured tissues and assisting vascular smooth muscle remodeling." (PMID 34824593, 2021). "The common parts of the KEGG enrichment pathways were further extracted, and Lipid and atherosclerosis, Nonalcoholic fatty liver disease, TNF signaling pathway, and MAPK signaling pathway were the main common factors." (PMID 34899351, 2021). "These cells produce proinflammatory mediators such as TNF-α and interleukin 1ß, which play a key role in the development and exacerbation of atherosclerosis." (PMID 34252115, 2021). "The ENTRACTE study showed that the anti-TNF-alpha antagonists, etanercept and adalimumab, yield beneficial effects in atherosclerosis, blunting the progression of the subclinical disease via a decrease in ICAM and asymmetric dimethylarginine levels." (PMID 34205487, 2021). "The downregulated pathways involved cytokine-cytokine receptor interaction, fluid shear stress and atherosclerosis, TNF signaling pathway, chemokine signaling pathway, and Th1 and Th2 cell differentiation." (PMID 34045967, 2021). "The efficacy of TNF blockade therapy in reducing or containing subclinical atherosclerosis was confirmed by other studies." (PMID 34527685, 2021). "In preclinical models of diet-induced atherosclerosis in mice, a combination of freeze-dried fruit and vegetable powder decreased serum TNF-α at a dose of approximating eight to nine servings/day in humans." (PMID 34829601, 2021).
atherosclerosis (continued). "TNF-α is a key pro-inflammatory mediator in the pathogenesis of RA that promotes the development of atherosclerosis." (PMID 35056068, 2021). "It was shown thatthe pro-inflammatory cytokines such as IL-6, IL-1βand TNF-α, can induce VSMCs migration/proliferationand hypertrophic response, which can take part in theexpansion of atherosclerosis." (PMID 34096220, 2021). "This is also the case for other proinflammatory cytokines involved in inflammatory signaling to vascular dysfunction in atherosclerosis, including tumor necrosis factor (TNF) and interleukin-1 (IL-1)." (PMID 34311709, 2021). "Cytokines involved in human atherosclerosis can be broadly classified as pro-inflammatory and pro-atherogenic (such as IL-1, IL-6, and TNF) or as anti-inflammatory and anti-atherogenic (such as IL-10 and IL-1rA)." (PMID 34076144, 2021). "Tumor necrosis factor alpha (TNF-a) is currently recognized as a vascular endothelial inflammatory factor, a crucial factor in promoting vascular endothelial injury that leads to atherosclerosis." (PMID 34260532, 2021). "Inflammatory factors IL-6 and TNF-α play an essential role in all the stages of atherosclerosis, including plaque formation, progression, and rupture." (PMID 34867337, 2021). "The latest stages in atherosclerosis are characterized by plaque destabilization, endothelial erosion, and atherothrombosis; of importance, TNF-α has shown effects on all these processes." (PMID 33770265, 2021). "On the other hand, the injured ECs produce pro-inflammatory cytokines such as TNF-α to promote phenotypic modulation, proliferation and migration of VSMCs to further aggravate atherosclerosis." (PMID 34262908, 2021). "Most research has been conducted on the inflammatory cytokine TNFα, which is known for its disease-aggravating role in atherosclerosis." (PMID 33572939, 2021). "The main pathways involved are pathways in cancer, fluid shear stress and atherosclerosis, and TNF signaling pathway." (PMID 33815556, 2021). "Some research has suggested that inflammation plays a role in the process of atherosclerosis, through an increase in the expression of proinflammatory cytokines and adhesion molecules (such as the tumour necrosis factor alpha [TNFα] and interleukin 6 [IL-6])." (PMID 35054229, 2021). "KEGG enrichment analysis revealed that the pathways of GXSTC on CBVDs were predominantly involved in AGE-RAGE, HIF-1, TNF, IL-17 signaling pathways, fluid shear stress, atherosclerosis, and apoptosis etc." (PMID 34054530, 2021). "It leads to increased oxidative stress and elevated levels of inflammatory cytokines, such as tumor necrosis factor-α (TNF-α), yielding phenotypic changes in smooth muscle cells and promoting the development of atherosclerosis and CV disease in IBD patients." (PMID 33924727, 2021). "Some studies suggest that hydroxychloroquine also reduces the production of cytokines important in the pathogenesis of atherosclerosis, such as interleukin-1 and 6 and tumor necrosis factor alpha (TNF-α)." (PMID 34535165, 2021). "Here, we demonstrated that elevated Hcy inhibits the expression of miR‐195‐3p, which in turn enhances IL‐31 expression and thereby causes the secretion of macrophages pro‐inflammatory factors IL‐1β, IL‐6 and TNF‐α and accelerate atherosclerosis." (PMID 34592792, 2021). "Our study shows that the expression levels of CD45, IL-1β and TNF-α are significantly increased in human coronary atherosclerotic lesions, which indicates that inflammation plays an important role in atherosclerosis." (PMID 34320932, 2021). "We further found that fluid shear stress and atherosclerosis, the TNF signaling pathway, the HIF-1 signaling pathway, and other signaling pathways play a role in the regulation of hyperlipidemia." (PMID 34746316, 2021). "Uncontrolled TNFα/IL-1β signaling has been shown to contribute to numerous diseases, including RA, Crohn's disease, atherosclerosis, cancer, and autoimmune diseases." (PMID 33776573, 2021).